LHPP (phospholysine phosphohistidine inorganic pyrophosphate phosphatase)
Diseases named in the same sentence as LHPP in open-access papers (continued):
Sharing a sentence is not in itself a finding about the gene and the disease.
tumor (34 papers, 2020 to 2025). "Blocking the histidine phosphorylation of ACO2 by the H73N mutation and the pHis phosphatase LHPP prevents UM tumor growth." (PMID 40988976, 2025). "Given the pivotal role of LHPP in the risk score, further research on its function within the tumor immune microenvironment and cancer cell stemness characteristics is of critical importance." (PMID 40240758, 2025). "In summary, silencing the histidine phosphorylation of ACO2 via the H73N mutation or the pHis phosphatase LHPP inhibited UM tumor growth in vivo." (PMID 40988976, 2025). "Dysregulation of LHPP, particularly its downregulation has been implicated in the pathogenesis of several cancers, associated with tumor progression and poor prognosis." (PMID 39468431, 2024). "Despite its recognition as a tumor suppressor over the past five years, the underlying mechanisms by which LHPP influences oncogenesis remain largely obscured." (PMID 39261475, 2024). "In summary, according to our systematic pancancer analysis of the LHPP gene, we found a correlation between LHPP expression and clinical prognosis, immune cell infiltration, and tumor mutation burden for a variety of human cancers." (PMID 36376886, 2022). "Low expression of LHPP was closely associated with tumor size and postoperative metastasis of RCC patients." (PMID 33426063, 2020). "Our study indicated that high LHPP expression is closely associated with significant infiltration of antitumor immune cells and suppression of stemness characteristics, suggesting its role as a potential tumor suppressor gene in GC." (PMID 40240758, 2025). "KEGG and HALLMARK enrichment analyses of neoadjuvant sequencing data from our center indicated that low LHPP expression was associated with the enrichment of anti-tumor immune response pathways, including the PI3K-AKT-mTOR, JAK-STAT, and WNT-β-catenin signaling pathways." (PMID 40240758, 2025). "LHPP, a histidine phosphatase, has been implicated in tumour progression." (PMID 35568711, 2022). "An increasing number of studies have explained the molecular mechanisms of LHPP biological functions in the development of various tumor types, but the mutational features of LHPP protein still remain unknown." (PMID 36376886, 2022). "LHPP encodes for a histidine phosphatase that has been shown to function as a tumor suppressor." (PMID 33882817, 2021). "In subcutaneous xenograft mouse model, LHPP WT effectively suppressed tumor growth and resulted in a decreased tumor volume." (PMID 40988976, 2025). "In conclusion, LHPP plays a critical regulatory role in the stemness features and tumor immune microenvironment of GC, presenting a promising biomarker and potential therapeutic target for personalized treatment of GC." (PMID 40240758, 2025). "In contrast, HNF4A, RASSF1, SPARCL1, and LHPP are associated with favourable outcomes: HNF4A regulates hepatocyte differentiation, RASSF1 acts as a tumour suppressor, SPARCL1 inhibits angiogenesis and metastasis, and LHPP suppresses tumour growth." (PMID 41007296, 2025). "LHPP is a highly conserved histidine phosphatase that functions as a tumor suppressor in various cancers." (PMID 40240758, 2025). "On the other hand, our analyses identified tumour suppressors like LHPP that inhibit growth, and CYP3A4 emerges as a favourable HCC prognostic marker." (PMID 41007296, 2025). "LHPP can inhibit the proliferation, growth, and migration of tumor cells and promote apoptosis by participating in the regulation of various cellular signaling pathways and protein phosphorylation." (PMID 40240758, 2025). "Conversely, LHPP-knockdown MKN45 GC cells exhibited a statistically significant increase in tumor formation rate and number, along with increased tumor weight and volume, compared to the control group." (PMID 40240758, 2025). "Through multi-omics analysis, we further elucidated the role of phospholysine phosphohistidine inorganic pyrophosphatase (LHPP) in the tumor immune microenvironment." (PMID 40240758, 2025).
tumor (continued). "Subcutaneous injection of LHPP-overexpressing, LHPP-knockdown, and the corresponding control cell lines was performed in nude mice, and tumor formation rates and numbers were recorded." (PMID 40240758, 2025). "Among annotations of differentially enriched regions, we discovered that tumor suppressor genes such as LHPP, VGLL4, USP53, and CLDN6 had increased H3K9ac signals in their promoter regions under the metformin condition." (PMID 38831454, 2024). "Phospholysine phosphohistidine inorganic pyrophosphate phosphatase (LHPP) is a recently identified tumor suppressor gene, which plays a key role in the development of HCC." (PMID 38696452, 2024). "Here, LHPP inhibits tumor cell growth by promoting mitotic catastrophe through the p27/CyclinA/CDK2 signaling pathway in human esophageal cancer." (PMID 39063217, 2024). "Findings from this study provides further evidence for a tumor suppressor role of LHPP and potential therapeutic value of restoring the expression of LHPP by saRNA for the treatment of HCC." (PMID 38696452, 2024). "The obtained results indicated that overexpression of LHPP leads to inhibit metastasis and tumour growth as detected by decelerated growth in tumour volume." (PMID 38966068, 2024). "In this regard, a histidine phosphatase “Phospholysine phosphohistidine inorganic pyrophosphate phosphatase (LHPP)” can be considered for its role in tumor progression." (PMID 38966068, 2024). "LHPP not only inhibits tumor cell proliferation, metastasis, and invasion but also promotes apoptosis and regulates tumor cell metabolism." (PMID 38292328, 2024). "Phospholysine phosphohistidine inorganic pyrophosphate phosphatase (LHPP) has recently emerged as a novel tumor suppressor." (PMID 38292328, 2024). "The findings indicate that LHPP, functioning as a tumor suppressor, is downregulated in both GC tissues and cells." (PMID 38292328, 2024). "It is noteworthy that the tumour suppression effect of LHPP is induced by acetylation, which in turn is regulated by phosphatase inhibitors." (PMID 38966068, 2024). "Previous studies have posited LHPP as a potential tumor suppressor, with its downregulation correlating with the exacerbation of oncogenic pathways across various cancers." (PMID 39468431, 2024). "Several studies have also highlighted the crucial role of LHPP in tumor progression in other cancer types." (PMID 39063217, 2024). "Since then, the role of LHPP as a tumor suppressor gene in various cancers has received great attention." (PMID 38292328, 2024). "In this study, we designed and identified potent saRNAs that activated LHPP expression in HCC cells and caused inhibition of cell proliferation and tumor growth in a xenograft model." (PMID 38696452, 2024). "This highlights the complex regulatory mechanisms governing LHPP expression and stability, which are crucial for maintaining its tumor-suppressive function." (PMID 39261475, 2024). "LHPP, a phosphatase identified as a tumor suppressor, is notably underexpressed in various human malignancies." (PMID 39261475, 2024). "The decreased expression of LHPP suggests a reduction in its tumor-suppressive effects, potentially facilitating ESCC pathogenesis." (PMID 39468431, 2024). "Reintroducing the genetic information of LHPP and increasing its expression level can effectively inhibit the growth and metastasis of liver tumors, and significantly reduce the tumor load and liver function impairment." (PMID 38696452, 2024). "Collectively, our findings underscore the pivotal role of ACSL4-mediated lipid peroxidation and ferroptosis in mediating the tumor-suppressive activity of LHPP." (PMID 39261475, 2024). "This investigation underscores the central role of STAT3 as a regulator in ESCC, directly impacting LHPP expression and suggesting a regulatory loop crucial for tumor behavior." (PMID 39468431, 2024). "IHC analysis of the tumor model showed LHPP knockdown increased AKT phosphorylation and decreased ACSL4 levels." (PMID 39261475, 2024).
tumor (continued). "LHPP has been shown to be a new tumor suppressor, and has a tendency to be under-expressed in a variety of cancers." (PMID 38849383, 2024). "LHPP, a novel, recognized tumor suppressor, exerts a critical influence on the regulation of tumor cell proliferation and survival by modulating various signaling pathways with its phosphatase activity." (PMID 39261475, 2024). "Recent publications provided additional evidence that LHPP acts as a tumor suppressor in other cancers, including pancreatic cancer, glioblastoma and oral squamous cell carcinoma." (PMID 37626656, 2023). "The expression of LHPP correlated with HCC patients’ survival, indicating that LHPP has a tumor-suppressive function." (PMID 37626656, 2023). "Analysis of clinical tissue samples illustrated that compared with adjacent healthy tissues the LHPP expression level was lower in tumor tissues, and the expression status of LHPP was closely related to the differentiation degree of OSCC." (PMID 35002505, 2022). "Lastly, we discovered that as a tumor suppressor, LHPP can not only reduce cell viability, inhibit cell proliferation, migration and invasion, but also participate in cell apoptosis via PI3K/ Akt pathway." (PMID 35002505, 2022). "LHPP impedes tumor proliferation and metastasis and inhibits cancer progression through the PI3K/AKT pathway by regulating the phosphorylated AKT at Ser473 in multiple cancer types." (PMID 36376892, 2022). "Next, the mRNA expression level of LHPP between tumor and normal tissues was further verified using the TCGA database." (PMID 36484014, 2022). "In this context, we mainly elucidate LHPP as a new tumor suppressor, which can not only restrict cell proliferation, migration and invasion but also accelerate cell apoptosis via suppressing PI3K/AKT pathway in OSCC." (PMID 35002505, 2022). "Of them, only LHPP, a newly discovered tumor suppressor, appeared to be upregulated by ELOA and was selected for further validations." (PMID 36376892, 2022). "An mTOR inhibitor, AY-22989, attenuated the activation of the PI3K/AKT/mTOR pathway and suppressed the tumor malignant capabilities induced by LHPP knockdown." (PMID 36484014, 2022). "It was first observed in eukaryotes in 1962, and has attracted attention recently stimulated by the finding that the enzyme histidine phosphatase, LHPP, has a role as a tumor suppressor." (PMID 36048825, 2022). "The results of in vitro and in vivo experiments here provide the first evidence for LHPP to play a tumor suppressor effect in OSCC, indicating that LHPP is a new diagnostic marker and therapeutic target for OSCC." (PMID 35002505, 2022). "Overall, our study demonstrated that LHPP function as a tumor suppressor gene in GC by regulating the PI3K/AKT/mTOR pathway." (PMID 36484014, 2022). "To explore how LHPP molecules exert tumour biological functions, we performed an enrichment analysis of the protein modification functions of KEGG and GO." (PMID 35568711, 2022). "In conclusion, we found that LHPP acts as a tumour suppressor in GC by inhibiting cell proliferation, invasion, and drug resistance." (PMID 35568711, 2022). "After the overexpression of LHPP, tumour growth was inhibited, and the growth in tumour volume was significantly decelerated compared with that in the control group." (PMID 35568711, 2022). "To further verify the biological functions of LHPP in vivo, we constructed a subcutaneous tumour model in nude mice to evaluate the effect of LHPP on the tumorigenic ability of GC cells in vivo." (PMID 35568711, 2022). "Consistently, our previous study revealed that patients with higher LHPP expression exhibited smaller tumor size, lower TNM stage and better prognosis." (PMID 36376886, 2022). "In conclusion, functional studies indicated that LHPP is a tumor suppressor that inhibits CRC proliferation and metastasis in vivo and in vitro." (PMID 34608127, 2021).
tumor (continued). "In the previous research, LHPP protein overexpression was highly related to better prognosis and lower tumor–node–metastasis classification of patients with CRC." (PMID 34608127, 2021). "It was found that LHPP mRNA and protein expression were also increased in tumor tissues containing LV-GAS5." (PMID 33418541, 2021). "Phosphorylated AKT was consequently confirmed as the downstream of METTL3/YTHDF2/LHPP/NKX3–1 to induce tumor proliferation and migration." (PMID 33121495, 2020). "Accumulating evidence suggests that LHPP acts as a tumor suppressor during the progression of various cancers, suppressing the proliferation and metastasis of cancer cells." (PMID 33426063, 2020). "LHPP is a kind of histidine phosphatases, acting as a tumor suppressor in the progression of various cancers." (PMID 33426063, 2020). "Our findings suggested that LHPP expression was lower in cancer tissues than that in normal pancreatic tissue, and its expression was also related to the degree of tumor cell differentiation and lymphocyte metastasis." (PMID 32186702, 2020). "Reduced expression of LHPP was positively correlated with tumor size and postoperative metastasis of RCC patients." (PMID 33426063, 2020). "Decreased expression of LHPP was closely correlated with tumor size and postoperative metastasis of RCC patients." (PMID 33426063, 2020). "We performed immunohistochemical analyses of PaCa tissues and matched normal tumor tissues from 36 patients to investigate the LHPP expression levels." (PMID 32186702, 2020). "Our study showed that LHPP expression may be related to the infiltration of immune cells into the tumor microenvironment, suggesting that LHPP may regulate the immune microenvironment through multiple mechanisms." (PMID 40240758, 2025). "To investigate whether the antitumor effect of LHPP is mediated via the alteration of ATP generation in tumor cells, we measured the ATP level in UM Mum2b cells after LHPP overexpression." (PMID 40988976, 2025). "We identified mitochondrial LHPP as a critical tumor suppressor involved in lipid metabolism." (PMID 40988976, 2025). "Among the 39,312 UM tumor single cells, only 524 LHPP-positive UM tumor cells were annotated." (PMID 40988976, 2025). "Thus, the expression of LHPP WT prevents UM cell proliferation and tumor growth both in vitro and in vivo, suggesting that the protein histidine phosphatase LHPP functions as a tumor suppressor in the rare ocular disease UM." (PMID 40988976, 2025). "Most studies suggest a metastasis suppressor function for LHPP, but LHPP may also play a role as a promoter of tumor progression." (PMID 39063217, 2024). "The LHPP-silenced group showed significantly enhanced tumor growth." (PMID 39261475, 2024). "LHPP has the potential to be a tumor biomarker and therapeutic target for hepatocellular tumors." (PMID 38696452, 2024). "Our research data indicate that LHPP is underexpressed in PCa cells and acts as a tumor suppressor, which could significantly inhibit the progression of PCa cells." (PMID 39261475, 2024). "Phospholysine phosphohistidine inorganic pyrophosphate phosphatase (LHPP) is a recently identified HCC tumor suppressor gene which plays an important role in the development of HCC and its inactivation and reactivation has been shown to result in respectively HCC tumorigenesis and suppression." (PMID 38696452, 2024). "Interestingly, we recently revealed that ELOA was downregulated in CRC and inhibited CRC progression by activating the transcription of LHPP, a putative tumor suppressor." (PMID 37694492, 2023). "In summary, our pancancer analysis among various tumor types could provide a comprehensive understanding of LHPP biological function in the progression of malignant diseases and promote the development of novel therapeutic targets." (PMID 36376886, 2022).
tumor (continued). "Consist with previous articles 7, 9, 16, our findings further confirmed the anti-tumor role of LHPP in GC, and may provide new insight into the mechanisms by which LHPP regulates GC cells progression." (PMID 36484014, 2022). "In summary, our study demonstrated that LHPP suppressed proliferation, migration, invasion and tumor formation of GC cells via regulation of the EMT in vitro, and the mechanism may be related to regulation of the PI3K/AKT/mTOR pathway." (PMID 36484014, 2022). "We reveled ELOA as a novel transcription regulator for LHPP, a newly identified tumor suppressor." (PMID 36376892, 2022). "We further used IHC to consolidate LHPP expression in tumours." (PMID 35568711, 2022). "In addition, we recently conducted a comprehensive bioinformatics analysis of LHPP gene function in pan-cancer by using the Cancer Genome Atlas (TCGA) database, the GTEx database, and the Clinical Proteomic Tumor Analysis Consortium (CPTAC) database." (PMID 36484014, 2022). "LHPP was found to pronouncedly decrease in tumor samples compared to normal tissues." (PMID 36484014, 2022). "Generally, we found that LHPP expression levels were impaired in the majority of human tumors, which suggested that the LHPP gene might serve as a tumor suppressor." (PMID 36376886, 2022). "Until recently, researchers found LHPP function as a tumor suppressor gene in multiple cancers." (PMID 36484014, 2022). "Cell counting Kit 8 test, EdU proliferation test, scratches test, invasion test, monoclonal formation test, mouse xenograft tumor model, HE staining and immunohistochemistry showed that LHPP inhibited OSCC growth, proliferation and migration in vivo and in vitro." (PMID 35002505, 2022). "Bioinformatics analyses of public databases revealed that LHPP may affect tumour glycolysis through acetylation." (PMID 35568711, 2022). "In addition, we utilized the GEPIA2 online tool to reveal the relationship between LHPP expression and tumor pathological stages." (PMID 36376886, 2022). "Given the mentioned results, it is speculated that LHPP is likely to play an anti-tumor role in OSCC." (PMID 35002505, 2022). "Therefore, we first utilized different bioinformatics tools to explore the tumor inhibitory role of LHPP protein across 33 tumor types based on the TCGA project." (PMID 36376886, 2022). "These conclusions suggested that LHPP might be a tumor inhibitor for developing novel therapeutic targets." (PMID 36376886, 2022). "This research further supported the tumor-suppressor role of LHPP in CRC." (PMID 34608127, 2021). "Thus, in this study we found that YTHDF2 as a crucial m6A reader exerted its degradation function by targeting two tumor suppressors LHPP and NKX3–1, consequently inducing AKT phosphorylation in PCa." (PMID 33121495, 2020). "LHPP, an enzyme protein, is a recently discovered tumor suppressor." (PMID 32904557, 2020). "In addition, decreased expression of LHPP was positively correlated with tumor size and postoperative metastasis of RCC patients." (PMID 33426063, 2020). "Moreover, a low level of histidine phosphatase LHPP was correlated with high PRAME expression in PRAME-positive UM tumor cells, but opposite phenomenon as high level of histidine kinase (NME1 and NME2), which indicates that low LHPP expression forebodes a risk of easier metastasis." (PMID 40988976, 2025). "Overall, high LHPP expression was significantly associated with altered tumor immune infiltration characteristics, showing a positive correlation with the infiltration abundance of CD3+, CD4+, CD45+ T cells, and CD8+, in both the center of the tumor and the invasive margin." (PMID 40240758, 2025). "Moreover, LHPP overexpression inhibited xenograft tumor growth in vivo." (PMID 40619414, 2025). "Furthermore, STAT3's profound impact on the cellular inflammatory environment, highlighted by increased IL6 levels, may directly foster alterations in the tumor microenvironment, thereby affecting the phosphorylation and functional dynamics of LHPP." (PMID 39468431, 2024).